SIRT2 (sirtuin 2)
Diseases named in the same sentence as SIRT2 in open-access papers (continued):
Sharing a sentence is not in itself a finding about the gene and the disease.
tumor (continued). "Based on the controversial roles of SIRT2 in EC risk and progression, we speculate that the downregulation of SIRT2 may be an adaptive strategy of tumor cells to evade immune surveillance and thus promote cell proliferation and metastasis." (PMID 37723477, 2023). "Ultimately, we concluded that Sirt2 is a tumor promotor, but only in an in vivo HCC context." (PMID 37628798, 2023). "Additionally, the co‐administration of the SIRT2 inhibitor SirReal2 with the PI3K/mTOR inhibitor VS‐5584 exhibited enhanced anti‐tumor properties against AML cells." (PMID 37658623, 2023). "Furthermore, the recent study examined selective SIRT2 inhibitors as an augmentation to tumor immunotherapy due to their ability to activate tumor-infiltrating lymphocytes." (PMID 36678624, 2023). "However, Sirt2−/− HCC livers appeared to contain more diffuse, less dense tumor nodules than Sirt2+/+ HCC livers." (PMID 37628798, 2023). "Similarly, there is evidence for SIRT2 as both a suppressor and promoter of tumour growth, though these roles are likely to be context dependent." (PMID 38009412, 2023). "More research will need to be carried out to determine whether Sirt2 is a tumor suppressor, as data suggest, in a normal liver context." (PMID 37628798, 2023). "Likewise, the lack of transcript changes overall indicated that any effect of Sirt2 on tumor growth was probably occurring at a post-transcriptional level, in accordance with its role as a lysine deacetylase." (PMID 37628798, 2023). "Immunoblot analysis revealed that Sirt2 proteins are expressed in both tumor and adjacent non-tumor liver tissues; however, HBV-associated HCC-biopsied tumor liver tissue expressed increased levels of Sirt2 as compared with adjacent non-tumor tissue." (PMID 38239506, 2023). "Specifically, SIRT2 has been considered indispensable during carcinogenesis; however, there is now a significant controversy regarding whether SIRT2 is an oncogene or a tumor suppressor." (PMID 37698780, 2023). "To verify whether four EMT-related genes (SIX1, SIRT2, CDKN2A and PGR) are associated with tumor metastasis, we performed transwell migration assays, transwell invasion assays and wound healing assays to investigate their relationship." (PMID 37723477, 2023). "The implication of SIRT2 in carcinogenesis and tumor progression remains controversial." (PMID 36453571, 2023). "Our previous data showed that SIRT2 deacetylates and stabilizes FGL1, thus suppressing tumor immunity, suggesting that SIRT2 and acetylation of FGL1 may play an important role in the development of HCC." (PMID 37115693, 2023). "In the present study, we asked whether the presence of Sirt2 slows or enhances tumor growth in a c-MYC-driven mouse model of HCC." (PMID 37628798, 2023). "The tumor suppression ability has also been reported for SIRT2 and SIRT3." (PMID 36769283, 2023). "Pharmacologic inhibition of SIRT2 enhanced antitumor immunity by promoting metabolic reprogramming toward a profound hyper-metabolic state with enhanced capacity for aerobic glycolysis in tumor-infiltrating T cells." (PMID 37165408, 2023). "Moreover, the protein levels of PLK‐1, CCNB1, CCNB2, and SIRT2 were observed to decrease in a dose‐dependent manner in tumor tissues following treatment with VS‐5584 in comparison to the control group." (PMID 37658623, 2023). "However, SIRT2 has also been paradoxically reported to have an oncogenic role or both oncogenic and tumor suppressive roles in other cancer types, including colorectal cancer." (PMID 35264593, 2022). "According to the association between SIRT2 expression and tumor immune infiltration, we speculate that SIRT2 may be involved in regulating tumor immunology." (PMID 36844923, 2022). "SIRT2 knockdown experiments in mice, however, reveal a robust tumor suppressor role for SIRT2." (PMID 35054489, 2022).
tumor (continued). "However, compared with paired adjacent non-tumor tissues, the redetermination of the TCGA data revealed SIRT2 was highly expressed in CHOL, HNSC, KICH, KIRC, and LIHC, but significantly lower in BRCA, KIRC, LUAD, UCEC, and slightly lower in LUSC tissue." (PMID 36844923, 2022). "In addition, systemic SIRT2 has been suggested to promote tumor development by suppressing NK cells." (PMID 35845599, 2022). "It was shown that SIRT2 knockdown significantly inhibited tumor growth." (PMID 36344502, 2022). "In addition, the deacetylation of lactate dehydrogenase (LDH) by SIRT2 increases its enzymatic activity, leading to the accumulation of lactate and promoting tumour cell proliferation." (PMID 36101744, 2022). "LUAD patients with a high level of SIRT2 expression have a high level of effector memory T cell, resident memory T cell, T cell exhaustion, resting Treg, Th1, monocytes, and DCs infiltrating into the tumor tissue (AD)." (PMID 36844923, 2022). "SIRT2 acts as a tumor suppressor in BC by regulating mitosis and genome integrity." (PMID 36581622, 2022). "For instance, sirtinol, the dual inhibitor of SIRT1 and SIRT2 that identified through phenotypic screening, has shown inhibitory effects on several tumor cell lines such as human breast cancer MCF-7 cells, lung cancer H1299 cells, human T cell leukaemia MT-2 cells." (PMID 36060706, 2022). "Thus, high levels of NAD+ in the tumor microenvironment are required for Sirt2 activation and, in turn, for T cell differentiation and for achieving powerful anti-tumor immune response." (PMID 33936090, 2021). "Furthermore, despite the enhancing effect of NK cell depletion on tumor volume and growth rate in wild-type littermate mice, this effect was diminished in SIRT2-overexpressing mice." (PMID 34155309, 2021). "Studies showed that SIRT1 and SIRT2 might be anticipated to assist tumor triggering, growth, and drug resistance." (PMID 33705642, 2021). "Furthermore, the results of IHC staining against SIRT2 antibodies shows that SIRT2 expression in the DUb-treated xenograft tumor is significantly increased as compared with control." (PMID 35177983, 2021). "Cell intrinsic SIRT2 could act as a tumor suppressor during initiation through DNA repair and genomic stability while systemic SIRT2 promoting progression of established tumors through NK cell suppression." (PMID 34155309, 2021). "Consistent with reports from other studies, antibody-mediated NK cell depletion in WT mice significantly promoted tumor progression compared to untreated control group, as evidenced by a 1.6-fold increase in tumor volume, and similar to that of Sirt2-KI mice (P = 0.0009)." (PMID 34155309, 2021). "SIRT2 KO mice developed normally at a young age but exhibited tumorigenesis in multiple tissues at an advanced age, suggesting an essential role of SIRT2 in maintaining genetic stability and repressing tumor formation." (PMID 33393735, 2021). "Importantly, pharmacologic inhibition of SIRT2 suppressed tumor progression, identifying a potential therapeutic target." (PMID 34155309, 2021). "Together, these results suggest that SIRT2 may directly regulate NK cell function, and they support the working model that increased systemic SIRT2 promotes tumor progression by inhibiting NK cell proliferation, migration, activation, and anti-tumor function." (PMID 34155309, 2021). "By removing K-Ras4a KFA, SIRT2 serves a tumor promoting role." (PMID 34368168, 2021). "SIRT2 has also been shown to increase Nrf2, an inducer of NK-cell-mediated tumor surveillance." (PMID 34155309, 2021). "With further study of the relationship between SIRT2, NK cells, and tumor progression, a new target for the challenges of immunotherapy could be developed." (PMID 34155309, 2021). "On the other hand, although it has been known that SIRT2 acts as a major character in carcinogenesis, whether it has been attributed to both tumor-promoting and tumor-suppressing activities is unclear." (PMID 33705642, 2021).
tumor (continued). "To investigate the mechanism of enhanced tumor progression observed with overexpression of systemic SIRT2, we examined whether SIRT2 expression influenced the composition of the tumor microenvironment." (PMID 34155309, 2021). "While our study provides evidence of SIRT2’s promotion of tumor progression through NK cell suppression, other immune cells, including T cells, may also be affected by SIRT2 expression." (PMID 34155309, 2021). "Therefore, the dual role of (promotor or suppressor) SIRT1 and also SIRT2 in modulating the tumor, makes them very attractive." (PMID 33705642, 2021). "Our findings have suggested that SIRT2 may participate in tumor immune response by regulating T cell differentiation." (PMID 33061819, 2020). "Furthermore, inhibition or downregulation of SIRT2 leads to the induction of apoptosis in many tumor cell lines." (PMID 32697192, 2020). "Furthermore, loss of SIRT2 and the resulting impaired activity in both APCCDH1 and APCCDC20 complexes, or the loss of CDH1 itself, promotes genomic instability and tumor progression, indicating that generalized APC dysfunction is tumorigenic." (PMID 32805721, 2020). "This implied that HRD1 might promote tumor cell growth by promoting the ubiquitination and degradation of SIRT2 and that SIRT2 functions as a tumor suppressor." (PMID 31932479, 2020). "Taken together, these results suggest that SIRT2 might serve as a tumor suppressor in carcinogenesis but as an oncogene during tumor development." (PMID 33207824, 2020). "In addition, Transwell assays showed that compared with the SW620‐control group, the number of tumour cells migrating or invading out of the chamber after SIRT2 overexpression was significantly lower." (PMID 32697380, 2020). "Taken together, these results suggest that SIRT2 participate in tumor immune response by regulating T cell differentiation, which may provide novel insight for tumor prevention and immune therapy." (PMID 33061819, 2020). "Previously, SIRT2 has been considered indispensable during carcinogenesis; however, there is now a significant controversy regarding whether SIRT2 is an oncogene or a tumor suppressor." (PMID 33014852, 2020). "In addition, the GEO dataset reveals that the mRNA levels of SIRT2 were significantly downregulated in the tumor samples of NSCLC patients, compared with those of the normal type." (PMID 32104503, 2020). "On the other hand, Sirt2 has also been reported to have tumor-promoting activity." (PMID 31324785, 2019). "In tumorigenesis, SIRT2 shows both tumor suppressor and oncogenic activities." (PMID 30761005, 2019). "The observed higher levels of Sirt2 could potentially deacetylate RRM2 to increase RNR activity in tumor tissues." (PMID 31324785, 2019). "The majority of our experiments employed H1299 cells derived from non-small cell lung cancer (NSCLC), therefore, it was of interest to test whether Sirt2 is upregulated in tumor tissues from patients with NSCLC." (PMID 31324785, 2019). "In addition, SIRT2 is reported to directly interact with β-catenin thereby altering the expression of genes like MMPs during tumor angiogenesis." (PMID 32010617, 2019). "Sirt2 functions as a tumor suppressor through its role in regulating mitosis and genome integrity." (PMID 31324785, 2019). "Also, it is observed that, SerRS (seryl-tRNA synthetase) plays tumor suppressor and anti-angiogenic role by collaborating with SIRT2 to antagonize c-Myc, a known angiogenic and oncogenic gene." (PMID 32010617, 2019). "In addition, treatment of PARP1-KO Jurkat cells with APO866 resulted in upregulation of 6 powerful antioxidant genes, including CAT and genes known to increase tumor cell survival such SIRT2 and UCP2." (PMID 31803365, 2019). "We showed that silencing SIRT2 significantly suppressed tumour angiogenesis." (PMID 30584257, 2018). "There is increasing evidence supporting an important role of SIRT2 in tumour development." (PMID 30584257, 2018).
tumor (continued). "We were interested in exploring whether STAT3 was involved in tumour angiogenesis mediated by SIRT2 in CRC, so we conducted related experiments." (PMID 30584257, 2018). "Furthermore, to test the role of the STAT3 pathway in tumour angiogenesis mediated by SIRT2, we collected CM from each group." (PMID 30584257, 2018). "Given the critical role of angiogenesis in tumour progression, we asked whether SIRT2 contributed to tumour-induced angiogenesis." (PMID 30584257, 2018). "The size and weight of tumor tissues derived from SIRT2-WT-iPSCs and SIRT2-KO-iPSCs were similar." (PMID 30166528, 2018). "Given that the phosphorylated STAT3 acts as a transcription factor by translocating to the nucleus to activate genes involved in tumour angiogenesis, we detected whether SIRT2 mediates the phosphorylation of STAT3 in the nucleus." (PMID 30584257, 2018). "In addition, a series of in vitro and in vivo experiments were performed to demonstrate the role of SIRT2 in tumour angiogenesis." (PMID 30584257, 2018). "Thus, SIRT2 and MYC are implicated in tumour metabolism regulation of MYC-induced malignancies working as a positive feedback loop." (PMID 30356832, 2018). "Importantly, a series of rescue experiments suggested that the function of SIRT2 in tumour angiogenesis depends on the STAT3/VEGFA signalling pathway." (PMID 30584257, 2018). "Significantly lower levels of SIRT2 in tumor tissues were expressed compared to normal." (PMID 29262808, 2017). "Moreover, overexpression of SIRT2 seemed to decrease tumor clone formation in A549 cells, while depletion of SIRT2 seemed to increase tumor colony formation in A549 cells." (PMID 26942878, 2016). "Interestingly, SIRT2 functions as both tumor suppressor and oncogene dependent on different tumor grade in breast cancer." (PMID 27916001, 2016). "Furthermore, Sirt2-/--KrasG12D serial lung sections showed nests of tumor cells exhibiting increased in vivo pERK and Ki-67 staining, implying increased KRAS activity and tumorigenicity in the lungs when Sirt2 is deleted." (PMID 27637077, 2016). "However, SIRT2 has been demonstrated as a tumor suppressor through its role in regulating mitosis and genome integrity." (PMID 27539227, 2016). "Recent studies indicated that SIRT2 might also act as a tumor promoter or tumor suppressor in tumorigenesis, likely displaying a regulatory function." (PMID 27226812, 2016). "Taking into account the regulatory role of SIRT2, we present here evidence to further establish the tumor suppressor role of SIRT2 in a KRAS-specific context by proposing that the acetylation status of K147 may direct activity and transformative properties." (PMID 27637077, 2016). "In addition, this study confirmed the tumor suppressor effect of this sirtuin since SIRT2 knockout mice presented an increased tumor growth in DMBA/TPA-induced skin carcinogenesis." (PMID 26437418, 2015). "This evidence would suggest that sirtuins also have the potential to act as tumour suppressors, and it has been hypothesised that both SIRT2 and SIRT6 act in such a manner." (PMID 26121130, 2015). "We speculate that SerRS also functions as a tumor suppressor by collaborating with SIRT2 to antagonize c-Myc." (PMID 24940000, 2014). "Small molecule SIRT2 inhibitors have in some cases selectively induced tumor cell death." (PMID 24259290, 2013). "Discrepancies in the positive and negative associations of SIRT2 with tumor development are likely due to differences in cell type, developmental activation patterns for SIRT2 and substrate preferences." (PMID 24259290, 2013). "Specifically, SIRT1, SIRT2, SIRT6, and SIRT7 are implicated in promoting PCa progression, while SIRT5 displays a paradoxical role, simultaneously aiding DNA repair and inhibiting apoptosis, yet fostering tumor growth through androgen receptor (AR) interactions." (PMID 39796040, 2024). "Thus, treatment with FLS-359 induces known consequences of SIRT2 inhibition in tumor cells." (PMID 37317966, 2023).
tumor (continued). "Furthermore, SIRT2 protein levels correlated with tumor size." (PMID 37115693, 2023). "In different tumor types, SIRT2 may act as an activator or inhibitor." (PMID 36344502, 2022). "Therefore, the controversy makes SIRT2 a very interesting candidate for further tumor research." (PMID 36844923, 2022). "In addition to SIRT1, SIRT2 functions in a binary manner, as a tumor suppressor or promoter." (PMID 36581622, 2022). "Finally, 10 tumor related pathways were enriched amongst the top 20 ranked pathways in the MetaCore pathway map folder analysis, suggesting that proteins important in tumorigenesis are key SIRT2 targets." (PMID 35264593, 2022). "Importantly, SIRT2 functions may evolve from tumor initiation to progression with altered physiologic targets." (PMID 33014852, 2020). "To date, the role of SIRT2 in the immune response against tumor remains largely unknown." (PMID 33061819, 2020). "In addition, in the in vivo metastasis assays where cells were administered into nude mice through tail vein injection, we found that the enforced expression of SIRT2 prominently decreased the bioluminescence signals in SW620‐SIRT2 tumour‐bearing mice compared with those in SW620‐control mice." (PMID 32697380, 2020). "Recent studies found that SIRT2 may mainly act tumor suppressor by maintaining genome stability." (PMID 32158696, 2020). "However, higher SIRT2 expression in advanced tumor tissues portend poor prognosis underscoring that SIRT2 may act as an oncogene during tumor progression." (PMID 33014852, 2020). "Notably, SIRT2 has been described as both an oncogene and a tumor suppressor." (PMID 33014852, 2020). "Furthermore, SIRT2 could reduce the proliferation, migration, and invasion, serving as a tumor suppressor." (PMID 33207824, 2020). "Previous studies have suggested that SIRT2 may act as both a tumor promoter and suppressor." (PMID 31091806, 2019). "However, the role of SIRT2 in tumour angiogenesis is still unclear." (PMID 30584257, 2018). "We hypothesized that a possible link exists between SIRT2 and tumour angiogenesis in CRC." (PMID 30584257, 2018). "The results presented herein clearly showed that continual activation of STAT3 could completely reverse the inhibitory effect of SIRT2 inhibition on tumour angiogenesis, suggesting that the role of SIRT2 in tumour angiogenesis is dependent on the STAT3 signalling pathway." (PMID 30584257, 2018). "Moreover, re-expression of SIRT2 has been found to inhibit tumor cell growth in vitro." (PMID 26942878, 2016). "Moreover, an increasing proportion of evidence suggests tumor-suppressive functions of SIRT2." (PMID 25907989, 2015). "Thus, some sirtuins, such as SirT2 and SirT6, seem to work as tumor suppressors." (PMID 25397683, 2014). "Other studies have shown that the deacetylase sirtuin 2 (SIRT2) can stabilise fibrinogen‐like protein 1 (FGL1) protein levels and that FGL1 plays a crucial role in tumour immune evasion." (PMID 39778006, 2025). "K100 acetylation reduces PGAM2 activity, while SIRT2 deacetylates and activates PGAM2, increasing NADPH production and promoting tumour cell growth." (PMID 39778006, 2025). "While SIRT1, SIRT2, and SIRT6 can assume opposite functions in relation to the tumor context, SIRT3, SIRT4, and SIRT7 tend to function more in favor of tumors." (PMID 41425553, 2025). "Another study indicated that SIRT2 can also deacetylate KRAS at K147 and that its acetylation status directly regulates KRAS activity, ultimately inhibiting tumour growth and invasion." (PMID 39778006, 2025). "Concurrently, the SIRT2-mediated activation of phosphoenolpyruvate carboxykinase 1 (PEPCK1) promotes glycolysis and reduces E-cadherin expression, facilitating tumor cell invasion." (PMID 41428704, 2025). "Conversely, SIRT2, SIRT4, and SIRT6 generally exhibit tumor-suppressive functions by inducing apoptosis, inhibiting invasion, and counteracting oncogenic signaling." (PMID 40710366, 2025).